MIB1 (MIB E3 ubiquitin protein ligase 1)
Diseases named in the same sentence as MIB1 in open-access papers (continued):
Sharing a sentence is not in itself a finding about the gene and the disease.
tumor (continued). "Exploratory prognostic factors were evaluated and showed an association, however not significant, between tumor relapse and proliferative activity (as measured by MIB-1 expression determined in neuropathology specimen)." (PMID 34172069, 2021). "Given the important role of the Notch pathway in modulating tumor growth, cancer metastasis, and the tumor microenvironment, MIB1‐mediated ubiquitination of Notch ligands may affect all these tumor characteristics." (PMID 33793053, 2021). "Therefore, the MIB-1 labeling index seems to be also an important predictor of tumor recurrence in patients who underwent a sufficient surgical treatment." (PMID 34277695, 2021). "It was worth noting that the sarcomatous component of the tumor pathologically showed lower MIB-1 labeling index compared with those in previously reported SCP cases, which might account for the long-term survival of the patient." (PMID 32450860, 2020). "High POLE expression was associated with increased MIB-1 (encoded Ki-67), a proliferation marker, as well as high expression of cancer testis antigens (CTAs), tumor mutation burden (TMB), silent mutation rate, and non-silent mutation rate (all p < 0.001)." (PMID 32433714, 2020). "The robust expression of MIB1/Ki-67 may imply the highly proliferative nature of an aggressive tumor." (PMID 33384656, 2020). "Of the patients developing recurrence only 7% showed MIB-1 staining in ≤50% of the tumor cells." (PMID 32758242, 2020). "In addition, the cell proliferation marker, MIB-1 in the GSC xenografts corresponded to the patient tumours." (PMID 30644426, 2019). "COX2 expression is associated with the proliferation marker MIB1 and tumor extension but is not altered by regular use of ASA, NSAIDs, glucocorticoids or immunosuppressants." (PMID 31291992, 2019). "Analyzing NHERF1 reactivity at membrane level, its absence was observed in IDCs (p = 0.002) and positive lymph node status (p = 0.013); conversely mNHERF1 expression was significantly associated with tumor size ≤2 cm (p = 0.039) and MIB1 negative (p = 0.019)." (PMID 29716631, 2018). "The lack of nuclear NHERF1 was noticeably associated to tumor size > 2 cm (p = 0.014), while its presence was linked to MIB1 negative expression (p < 0.001)." (PMID 29716631, 2018). "Expression of Cyclin D1 was significantly higher in OIII (median expression 45% versus 14% for OII, p = 0.0006) and was correlated with MIB-1 expression (p<0.0001), vascular proliferation (p = 0.002), tumor necrosis (p = 0.04) and a shorter EFS in the total cohort (p = 0.05)." (PMID 29489901, 2018). "All cases included in this study were characterized for BRCA1/2 germline mutations, the major genetic risk factor for MBC, and for the main clinical-pathologic features including: family and personal history of cancer, ER, PR, HER2 and Ki67/MIB1 expression and tumor grade (G)." (PMID 29731982, 2018). "Histologic and immunohistochemical criteria of sarcomatous changes are cellular atypia, a fascicular pattern, ten mitoses per 10 high-power fields at × 40 magnification, decreased expression of CD34, and increased MIB-1 (EB1) with more than 5% of tumor tissue transformed." (PMID 28388964, 2017). "In addition, the tumor cell proliferation rate (or mitotic rate) which differs between low-grade or high-grade NEs was visualized through the MIB-1 antibody (Figure 1E1)." (PMID 27023611, 2016).
tumor (continued). "In addition, a correlation was found between the methylation status of CpG6 and CpG7 in the ABCG2 promoter in tumor-distant tissues and MIB-1 (r = 0.556, p = 0.025 and r = 0.550, p = 0.027, respectively)." (PMID 27689338, 2016). "Immunofluorescence analysis of tumors demonstrated that cisplatin reduced the percentage of cells positive for the proliferation marker, Ki67/mib-1 and increased cells showing expression of the apoptosis marker, cleaved caspase-3, consistent with effects on tumor burden." (PMID 26215403, 2015). "These patients may benefit from new treatment strategies targeted towards inhibiting tumour infiltration rather than proliferation, especially since some of these very infiltrative tumours exhibit few mitoses and scarce MIB1 positivity." (PMID 25047029, 2014). "In spite of all, in cases with residual tumour after surgery, immunohistochemical investigation of MIB-1 LI may be useful to indicate tumour growth and aggressiveness and to be in favour of therapeutic decision-making." (PMID 26019536, 2014). "MIB-1 protein was expressed in 69% of triple negative tumor cases (25/36)." (PMID 24586570, 2014). "The Ki-67 index, the proliferative activity with monoclonal antibody MIB-1, may show nuclear positivity in about 10% of tumor cells and 30 to 40% of tumor cells in areas with anaplastic features." (PMID 23915031, 2013). "As expected, we observed a strong positive correlation between the average expression of the genes comprising this cluster and Ki67 staining (by MIB1 antibody) and mitotic index, consistent with the notion that these genes quantify tumor proliferative capacity." (PMID 23618380, 2013). "MIB-1 is a Ki-67 immunostain that stains all actively growing cells, allowing for rapid, objective, and sensitive assessment of actively cycling cells within the tumor." (PMID 23346460, 2012). "HIF-1α expression showed a significant association with tumor grade 2 (p = 0.001), negative PR status (p = 0.013), high MIB1 (p = 0.020) and moderate NPI (p = 0.029)." (PMID 22439624, 2012). "MIB-1(Ki-67 antigen) labeling index showed 18.3 ± 5.6 supporting high proliferation of the tumor." (PMID 20398400, 2010). "The MIB-1 antibody for the Ki-67 antigen was positive in 6.6% of the tumor cells." (PMID 20628520, 2010). "This nuclear antigen expresses an epitope that is recognised by a murine monoclonal antibody known as MiB1, and therefore the number of Ki-67/MiB1-positive nuclei (termed the Ki-67/MiB1 index) can be used as a marker of cellular proliferation in paraffin-embedded tumour specimens." (PMID 21063399, 2010). "Ki67/Mib-1 is a proliferation marker highly expressed in the majority of tumours." (PMID 16740156, 2006). "Whereas Rac1 protein level was not significantly related to proliferation, highly proliferative tumours (i.e. >20% MIB-1 positive cells) showed a significant increase in the level of RhoA-like proteins as compared to tumours with low proliferation index (i.e. MIB-1 <5%) (P<0.05)." (PMID 12237774, 2002). "MIB-1 staining waspresent in 14.5% of tumor cells in all specimens (range 0–59%)." (PMID 18521206, 1997). "According to certain reports, the use of the proliferation tumor marker MIB-1 may be useful." (PMID 39790708, 2025). "Furthermore, Ki-67/MIB1 highlighted 1-2% of tumor cell nuclei (low)." (PMID 35642345, 2023). "High levels of MIB1/Ki-67 on histology may indicate aggressive feature of the tumor." (PMID 33384656, 2020). "MIB-1 labeling index is typically in 1 % to 3 %, but may increase to 5.8 % in the recurrent tumor." (PMID 28977976, 2017).
tumor (continued). "In addition, in familial BC we have found that high VEGF expression is significantly associated with poor tumor grade, MIB1 positive expression and negative ER and PR status." (PMID 26312763, 2015). "Thus, loss of these markers but not increased tumor size or higher proliferation rate Mib-1 defined a subgroup of SCLC with particularly poor prognosis." (PMID 25884169, 2015). "The question therefore remains as to whether the potential prognostic value of Ki-67/MiB1 is confined to certain treatment groups and if individuals with highly proliferative tumours as determined by their Ki-67/MiB1 index are likely to require more aggressive treatment regimens." (PMID 21063399, 2010). "Furthermore, MIB-1 LI positively correlated with tumour size (R=0.409, P<0.005)." (PMID 19156147, 2009). "Despite high proliferation indices (Mib-1 and Cyclin A) and the high degree of cytogenetic instability in ductal invasive grade 3 carcinomas with 7p-gains, the frequency of 16q-losses and the percentage of ER/PR+tumours were significantly higher compared to other subgroups." (PMID 15054466, 2004). "To take account of the distinct biology of various tumor types included in this cohort, however, we moreover compare tumor type-specific MIB-1 LI values and analyze the correlation of MIB-1 LI and PFS of various tumor types." (PMID 38580878, 2024). "To study the clinical significance of MIB-1 LI as a proliferative activity marker in PLGG, we analyzed the implication of MIB-1 LI on pre- and postoperative tumor growth velocity within our cohort." (PMID 38580878, 2024). "A higher rate for non-serviceable hearing was observed for age >/=55.47 years, preoperative tumor volume >/= 6.57 cm3, IAC widening >/= 1.2 mm and MIB1 immunopositivity >/= 1.2%." (PMID 38850456, 2024). "The maximum MIB-1 proliferation rate (34 ± 26%) was significantly positively correlated with the SUV (mean 9.8 ± 7.2, p = 0.005) and with the preoperative tumor volume (mean 474.7 ± 68.6 cm3, p = 0.047)." (PMID 39594712, 2024). "However, compared to preoperative tumor growth rates, a crucially decreasing correlation of MIB-1 LI values and tumor growth rates after surgical intervention and age-dependent correlation could be shown, subsequently resulting in a limited prognostic value of MIB-1 LI cutoffs regarding PFS in PLGG." (PMID 38580878, 2024). "The authors showed a correlation of Cho/NAA with MIB-1 and CD34 marker expression, as well as with tumor infiltration." (PMID 37345097, 2023). "Immunohistochemistry of the original and xenografted tumor revealed positivity for WT1, MIB1 (arrows: nuclear staining), Annexin IV." (PMID 33143664, 2020). "The analysis included clinical features such as age, gender, KPS score, chemotherapy, radiotherapy, and EOR degree in addition to the profiles of the MIB1 percentage and FLNC expression in patient tumour tissues." (PMID 30867563, 2019). "These comprised two truncating pathogenic variants—RB1 R255* and TSC1 R786*, one missense probable damaging variant—VHL tumor suppressor R58W, and four splice variants of unknown significance in ETS2 transcription factor, SGK1 serum/glucocorticoid regulated kinase 1, AXL RTK and MIB1." (PMID 31258848, 2019).
tumor (continued). "Location, extent of resection, presence of atypia, brain invasion, high MI, high MIB1 labelling, bone involvement, use of adjuvant radiotherapy and secondary progression from WHO I tumour." (PMID 29961125, 2018). "Surgical tumor samples were histopathologically analyzed for immunoexpression of MGMT, MSH6 and MIB-1." (PMID 28900805, 2017). "Immunohistochemical staining showed that most tumour cells were positive for WT-1, CD57, MIB-1, Vimentin, and EMA, while CK7 staining showed weak focal positivity." (PMID 25907695, 2015). "MIB-1 was 1% in both portions of the tumor, and nuclear INI-1 protein was retained in all tumor cells in both areas." (PMID 24321241, 2014). "Here we studied four immunohistochemical tumor markers (HBME-1, MIB-1, CK19, and Galectin-3) in thyroid of mice housed in the Mouse Drawer System and maintained for 90 days in the International Space Station." (PMID 25328888, 2014). "The preliminary results of our study demonstrated that Cho/NAA is closely related to MIB-1, CD34 and tumour infiltration in HGG." (PMID 22729482, 2012). "According to the WHO classification (2010), the tumor was diagnosed as “neuroendocrine tumor, NET G2,” because the Mib1 index (%) is 7% and proliferation rate is 4 mitoses per 10HPF,and the tumor was composed acinar and neuroendocrine cells." (PMID 22824559, 2012). "Age, tumour size and grade, lymph node involvement, peritumoral vascular invasion (PVI), status of hormone receptors (HRec), Her2, and Mib1 were considered." (PMID 20233435, 2010). "The MIB1/caspase 3 ratio (X), D90 (Y), and C90 (Z-axis) for each tumour were plotted separately for grade II and III and grade IV tumours." (PMID 15292940, 2004). "MIB1-PR was significantly correlated to grading (P = 0.018); SPF was significantly correlated with tumour size (P = 0.041) and inversely with steroid hormone receptor status (P = 0.03)." (PMID 9166949, 1997). "Considering previously published data, we aim to perform a comparative evaluation of tumor and endothelial cell proliferation in PitNETs using double immunohistochemistry for CD34/MIB1 (CD34 to identify endothelial cells and MIB1 to highlight proliferative cells)." (PMID 41614857, 2025). "In this retrospective study, we analyzed clinical data, tumor extension, cystic characteristics and immunohistochemical markers for inflammation (CD68, CD163, CD3, CD8) and proliferation (MIB-1) as potential factors influencing the EOR in 1007 surgically treated primary sporadic VS." (PMID 41044688, 2025). "Multivariable Cox regression confirmed this finding: incomplete resection was the only independent predictor of shorter PFS (HR 8.00, 95% CI 1.85–34.71), whereas tumor origin and MIB-1 ≥ 3% did not retain significance." (PMID 41382243, 2025). "This MIB1 LI-mediated reciprocal tumor stroma contact is unique to PRL-secreting and non-functioning PitNETs." (PMID 41614857, 2025). "Additionally, a group of E3 ubiquitin ligases, including HECTD3, MIB1 and FBW7 have been reported to inhibit tumor growth by targeting different ferroptosis related genes." (PMID 39557844, 2024).
tumor (continued). "IHC analysis, in mice receiving daily HIF-1α siRNA injections has confirmed the macroscopic image of reduction of tumor volume through the decreased levels of HIF-1α transcriptional targets, like VEGF, GLUT–1, c-MET, and CA-IX and markers for cell growth like MIB-1 and MVD." (PMID 39055895, 2024). "Ki-67 was detected by immunohistochemistry (Mib1) in approximately 25% of the tumor cells, the tumor cells did not express brachyury." (PMID 37171609, 2023). "We have now conducted volumetric tumor measurements of preoperative tumor size and growth in this cohort to further examine the possible proliferative effect of COX2 and proliferation marker MIB1 in VS." (PMID 33641674, 2021). "MKI67 is a well-known marker of cell proliferation, expressed both by tumor and nontumor cells, clinically determined by MIB1 or Ki67 IHC staining of WSIs." (PMID 32747659, 2020). "The majority of MBC cases are ER and PR positive (90.8% and 83%, respectively), HER2 and Ki67/MIB1 negative (84.2% and 61.7%, respectively) and have intermediate/moderate tumor grade (G2) (52.4%)." (PMID 29731982, 2018). "As a result, anti-tumor effects were significantly shown in xenografted tumors with YS110 and PMX combined treatment compared to tumors with single treatment of YS110 or PMX, which was accompanied by a significantly reduced MIB-1 index." (PMID 27134571, 2016). "In addition, positive correlations were found between MIB-1 and the methylation status of CpG6 and CpG7 in the ABCG2 promoter in the tumor-distant tissues." (PMID 27689338, 2016). "A total of 90% (32/36) of the triple breast negative tumor cases with MIB-1 immunoreactivity showed tumor size of more than 2 cm while lymph node positivity was involved in 72% of cases (26/36)." (PMID 24586570, 2014). "Stage III, MIB-1 immunoreactive, triple negative breast tumors were also strongly correlated with tumor size of more than 2 cm [p<0.000], axillary lymph node metastases [p<0.000] and tumor grade 3 [p<0.000; data not shown]." (PMID 24586570, 2014). "An inverse correlation of CYLD protein expression with mitotic activity (as assessed by the MIB1-index), but not with tumor stage, has been reported by others in human HCC." (PMID 25329885, 2014). "The protein was not present in normal mature cerebral parenchyma and had a tumour expression profile similar to that of Ki67/MIB1." (PMID 24039914, 2013). "Adachi reported that a patient aged under 40 years and the presence of a rhabdomyosarcomatous component correspond to a poor prognosis, but there is no significant prognosis difference with respect to gender, tumor site, tumor size, or MIB-1-labeling index." (PMID 21496258, 2011). "Tissue sections cut from formalin-fixed paraffin-embedded blocks from biopsy specimens and postoperative tumor tissues were stained for the presence of estrogen receptor (ER), progesterone receptor (PgR), HER-2 (human epidermal growth factor receptor-2), and MIB-1(Ki-67)." (PMID 19845944, 2009). "MIB-1 failed to predict PFS in recurrent tumours (P=0.1) and was not independent of hTERT status in predicting outcome in multivariate analysis." (PMID 18797459, 2008). "In our study the probability of pCR was higher, even if statistically not significant, in the case of hormone receptor-negative tumours (25 vs 9.7%), Mib-1 ⩾20% (17.4 vs 7.7%) and Her-2 overexpression (20 vs 4%)." (PMID 16052214, 2005). "The rate of proliferating (Mib-1 positive) epithelial cells was determined in 10 tumours (six nKAs and four mKAs) and seven control specimens of normal skin." (PMID 12439721, 2002).